PAK2 (p21 (RAC1) activated kinase 2)
Diseases named in the same sentence as PAK2 in open-access papers (continued):
Sharing a sentence is not in itself a finding about the gene and the disease.
colitis (1 paper, 2017). Inflammation of the colon. "To confirm our findings in vivo, we used a T cell transfer model of colitis to assess the ability of Pak2-deficient Tregs to suppress the development of wasting disease in syngeneic T cell-deficient hosts." (PMID 29213081, 2017). "Previously, our laboratory reported that Cd4-Cre mediated deletion of Pak2 in T cells resulted in a block in the development of thymic-derived and peripherally induced regulatory T cells (Tregs) coupled with the onset of spontaneous colitis, suggestive of a break in peripheral tolerance." (PMID 29213081, 2017).
congenital myopathies (1 paper, 2019). "The development of skeletal muscle disease in dKO mice raises the possibility that mutations in PAK1 and/or PAK2 may underlie human dystrophies or congenital myopathies." (PMID 30791960, 2019).
Cri-du-chat syndrome (1 paper, 2023). Monosomy 5p, also known as Cri du chat syndrome, is a rare autosomal deletion syndrome characterized by a mewing cry (cri du chat) in infancy, multiple congenital anomalies, intellectual disability, microcephaly, and facial dysmorphism. "Among these, there are a number of biomedically relevant genes, such as PAK2 affected by 3q29 microdeletion, CTNND2 affected in Cri-du-Chat syndrome, or MAPT affected by 17q21.31 microdeletion (inset)." (PMID 37164484, 2023).
endometrial cancer (1 paper, 2015). Primary or metastatic malignant neoplasm involving the endometrium (mucous membrane that lines the endometrial cavity). "Atrophic and secretory endometrium as well as endometrial cancers showed weak cytoplasmic and nuclear p-Pak2 expression whereas hyperplastic endometrium showed moderate cytoplasmic and nuclear p-Pak2 expression." (PMID 26218748, 2015). "Furthermore, there was significant reduced cytoplasmic and nuclear p-Pak2 expression in endometrial cancers than that in complex hyperplasia (P = 0.009 and P = 0.006, respectively) and pure atypical hyperplasia (P = 0.038 and P = 0.042, respectively)." (PMID 26218748, 2015). "Kaplan-Meier-survival analyses revealed that lower expression of cytoplasmic Pak4 (P = 0.026), but not Pak1, nuclear and cytoplasmic p-Pak2, nuclear Pak4, nuclear and cytoplasmic p-Pak4, resulted in a poorer survival in endometrial cancer patients." (PMID 26218748, 2015). "In this study, expression of Pak1, p-Pak2 Ser20, Pak4, pPak4 Ser474 in 21 normal endometrium, 16 hyperplastic endometrium without atypia, 17 atypical complex hyperplasia and 67 endometrial cancers was assessed by immunohistochemistry and correlated with clinicopathological parameters." (PMID 26218748, 2015).
gestational trophoblastic disease (1 paper, 2017). "Even when PAK2 had being poorly studied in PE, we know that it is directly involved in gestational trophoblastic disease and that endothelial cells PAK and/or CDC42 are directly involved with KDR and consequently essential for endothelial cells organization." (PMID 28789679, 2017).
Immunodeficiency (1 paper, 2022). Failure of the immune system to protect the body adequately from infection, due to the absence or insufficiency of some component process or substance. "The PAK2 gene plays an important role in the T cell receptor signaling pathway, human immunodeficiency, and signaling by receptor tyrosine kinases." (PMID 35783297, 2022). "Therefore, it is reasonable to postulate that the dysregulation of PAK2, TAP2, and PLCL1 genes is likely to elicit autoimmune reactions by altering antigen processing and presentation, T cell receptor signaling, and immunodeficiency pathways." (PMID 35783297, 2022).
Insulin resistance (1 paper, 2023). Increased resistance towards insulin, that is, diminished effectiveness of insulin in reducing blood glucose levels. "Previous studies have found that PAK2 is involved in neuronal insulin signaling, glucose uptake and insulin resistance." (PMID 37610708, 2023).
lung squamous cell carcinoma (1 paper, 2024). "Although p21-activated kinase 2 (PAK2) is an essential serine/threonine protein kinase, its role in the progression of lung squamous cell carcinoma (LUSC) has yet to be fully understood." (PMID 38828848, 2024).
lymph node metastasis (1 paper, 2014). "Multivariate regression analysis indicated that PAK2 expression (P = 0.01), pSer20PAK2 expressions (P = 0.01), depth of invasion (P = 0.002) and lymph node metastasis (P < 0.001) were independent prognostic factors." (PMID 24621074, 2014). "The univariate analysis showed that the following factors were significantly related to postoperative survival: depth of tumor invasion (P < 0.001), lymph node metastasis (P < 0.001), venous invasion (P < 0.001), PAK2 expression (P = 0.001) and pSer20PAK2 expressions (P = 0.001)." (PMID 24621074, 2014).
Lymphadenopathy (1 paper, 2017). Enlargement (swelling) of a lymph node. "Furthermore, Foxp3-Cre Pak2-deficient mice presented with splenomegaly, lymphadenopathy and severe thymic atrophy, suggestive of ongoing inflammation." (PMID 29213081, 2017).
lymphopenia (1 paper, 2014). Reduction in the number of lymphocytes. "We detected considerable expression of Pak2 in the CD44hi activated (or memory) cells, suggesting that residual CD44hi T cells had undergone lymphopenia-associated expansion from the few T cells that had escaped Cre-mediated deletion (data not shown)." (PMID 24843022, 2014). "T-cell specific Pak2 deletion using Lck-Cre or Cd4-Cre transgenes resulted in severe T cell lymphopenia." (PMID 24843022, 2014). "As a consequence, Cd4-Cre mediated Pak2 deletion results in severe T cell lymphopenia due to Pak2's multiple roles in T cell maturation and timed egress of thymocytes." (PMID 24843022, 2014).
lymphoproliferative disorder (1 paper, 2017). "The first evidence to suggest a role for Pak2 in Treg function followed the observation that Pak2F/F;Foxp3-Cre mice developed a severe and lethal multi-organ lymphoproliferative disorder, similar to that observed in scurfy mice possessing a mutation in the Foxp3 allele." (PMID 29213081, 2017).
malignant meningioma (1 paper, 2015). "NF2-null malignant meningioma KT21-MG1-Luc5D cells (hereafter referred to as KT21), were stably transduced with either empty virus or a virus encoding a Pak1 or Pak2 shRNA construct." (PMID 25596744, 2015).
mantle cell lymphoma (1 paper, 2017). Mantle cell lymphoma is a rare form of malignant non-Hodgkin lymphoma affecting B lymphocytes in the lymph nodes in a region called the ``mantle zone''. "The level of PAK2 is increased in mantle cell lymphoma (MCL) and in activated B‐cell like diffuse large B cell lymphoma (ABC‐like DLBCL) that harbour 3q29 amplifications." (PMID 28707321, 2017).
memory impairment (1 paper, 2024). "The double negative knock-out PAK mice showed memory impairments and PAK2 dysfunction led to autistic-like behaviors, reduced LTP, and decreased synaptic densities, implicating its increase might be beneficial in AD." (PMID 39050707, 2024).
mesothelioma (1 paper, 2023). A usually malignant and aggressive neoplasm of the mesothelium which is often associated with exposure to asbestos. "A recent study indicated that Nf2; Cdkn2a-deficient mouse mesothelioma cells showed less malignant phenotypes with PAK2 loss, suggesting that anti-PAK drugs may be promising for mesothelioma treatment." (PMID 37180489, 2023).
Miscarriage (1 paper, 2022). A pregnancy that ends at a stage in which the fetus is incapable of surviving on its own, defined as the spontaneous loss of a fetus before the 22th week of pregnancy. "Higher levels of cellular senescence-repair proteins, RPA-70, PSME-4, and PAK-2 were seen in placental EVs derived from missed miscarriage, but lower levels of the three proteins were seen in missed-miscarriage placentae, compared with healthy first-trimester placentae." (PMID 36139348, 2022). "The expression of RPA-70, PAK-2, and PSME-4 in missed-miscarriage placental explants that had been treated with GW4869 were significantly higher than in untreated placental explants from missed miscarriage, measured by a semiquantitative analysis." (PMID 36139348, 2022).
muscle disorders (1 paper, 2019). "However, variants that alter expression levels of PAK1 and/or PAK2 in humans could contribute to muscle disorders as modifier loci." (PMID 30791960, 2019).
myeloid leukemia (1 paper, 2026). A clonal proliferation of myeloid cells and their precursors in the bone marrow, peripheral blood, and spleen. "AML samples exhibited deregulated TOE1 expression versus normal hematopoietic stem/progenitor cells (HSPCs), and TOE1 depletion suppressed the proliferation of myeloid leukemia cell lines, and primary human HSPCs, partly through a p21-activated-kinase 2 (PAK2) mediated mechanism." (PMID 42030941, 2026).
myxofibrosarcoma (1 paper, 2023). A malignant fibroblastic neoplasm arising from the soft tissue. "Although PF3758309 is considered a pan-PAK inhibitor not targeting PAK1 alone 14, 33, this drug might indeed exert a notably specific repressive effect on PAK1-driven angiogenesis, an oncogenic attribute not redundantly phenocopied by PAK2-4, in myxofibrosarcomas at least." (PMID 37564209, 2023).
preeclampsia (1 paper, 2017). Preeclampsia is a hypertensive disorder of pregnancy that is characterized by new-onset hypertension with proteinuria presenting after 20 weeks of gestation, and depending on mild or severe forms may initially present with severe headache, visual disturbances, and hyperreflexia. "However, genes like HSP90, PAK2, CD247 and others included in the first 1% of the prioritized list need to be further explored in preeclampsia pathogenesis through experimental approaches." (PMID 28789679, 2017). "However, other genes like HSP90, PAK2, CD247 and others included in the first 1% of the prioritized list need to be further explored in preeclampsia pathogenesis through experimental approaches." (PMID 28789679, 2017).
prostatic adenocarcinoma (1 paper, 2017). "Human prostatic adenocarcinoma cells and skin epidermal cells that are subjected to epidermal growth factor‐induced transformation show reduced colony formation upon loss of PAK2." (PMID 28707321, 2017).
Pruritus (1 paper, 2021). Pruritus is an itch or a sensation that makes a person want to scratch. "Further analysis of the role of PAK2 in the development of cutaneous sensory nerves is needed to clarify the mechanism of pruritus development in AD." (PMID 33539470, 2021).
renal cell carcinoma (1 paper, 2023). "The renal cell carcinoma pathway included some already known phosphoproteins involved in RCC, such as PAK1, PAK2, and BRAF." (PMID 36997065, 2023). "These pathways included some already known phosphoproteins involved in renal cell carcinomas, such as PAK1, PAK2, and BRAF." (PMID 36997065, 2023).
skin cancer (1 paper, 2014). "PAK2 knockdown using shRNA also slowed down the proliferation of skin cancer cell lines." (PMID 24664099, 2014).
Stroke (1 paper, 2024). Sudden impairment of blood flow to a part of the brain due to occlusion or rupture of an artery to the brain. "We conclude that the circAnks1b/miR‐130b‐5p/Pak2 axis is a promising therapeutic target for protecting neurons in the peri‐infarct region and accelerating neurological recovery post‐stroke." (PMID 39328024, 2024).
Ventricular arrhythmia (1 paper, 2025). "Pak2 activation thus protects against ventricular arrhythmia associated with cardiac stress and hypertrophy, through unique mechanisms offering potential novel therapeutic anti‐arrhythmic targets." (PMID 40068092, 2025). "Together the findings suggest that modulating mitochondrial function and ROS production through targeting Pak2 may offer a strategy for managing ventricular arrhythmias and preventing SCD." (PMID 40068092, 2025). "Pak2 overexpression and the novel Pak2 activator JB2019A ameliorated these effects, enhanced cardiac function and decreased the frequencies of triggered ventricular arrhythmias." (PMID 40068092, 2025). "We then developed a mouse Pak2ctg model with inducible cardiac‐specific overexpression of wild type Pak2 driven by Myh6‐creERT to explore effects of Pak2 overexpression on acute isoproterenol or TAC‐induced ventricular arrhythmias." (PMID 40068092, 2025).
tumor (63 papers, 2012 to 2026). "In various cancers, high PAK2 expression is associated with tumor progression, metastasis and poor prognosis." (PMID 41423632, 2025). "Prior studies have shown that elevated PAK2 expression in multiple advanced cancers is closely associated with tumor progression and poor clinical outcomes." (PMID 41423632, 2025). "Furthermore, consistent results from three external datasets and proteomics data demonstrated elevated PAK2 expression in tumor tissues, further supporting its diagnostic potential." (PMID 41311809, 2025). "While PAK2 is widely implicated in tumorigenesis across diverse cancer types, its precise molecular mechanisms and downstream effectors vary significantly depending on the tumor context." (PMID 39769207, 2024). "PAK2 expression is associated with advanced tumor progression and poor prognosis." (PMID 39769207, 2024). "Furthermore, a mass spectrometry-based phosphoproteomic study comparing aggressive PCa cell lines, namely PC-3 and PC-3M, revealed that PAK2 was upregulated in highly metastatic cells, with its phosphorylation linked to enhanced tumor migration." (PMID 39769207, 2024). "Moreover, growth in a model for peritoneal metastasis was hampered when CMS4 tumor cells were deficient for PAK2." (PMID 36869386, 2023). "In addition, DCBLD2, CASP7, TSC22D1, ANXA7, PRKAR2A, ZMYND11, and PAK2 have been reported to be tightly linked to tumor malignancy in previous studies." (PMID 35513372, 2022). "PKM2-mediated phosphorylation of Ser192/197 is essential for maintaining PAK2 activity in PDAC cells, promotes HSP90 association with PKM2-PAK2 complex, which prevents the degradation of ubiquitin and protease of PAK2, and ultimately mediates tumor cell invasion, metastasis and cell proliferation." (PMID 31391918, 2019). "Some reports also revealed that PAK2 expression was closely associated with tumor malignancy and clinical outcome, which indicates that PAK2 may contribute to disease development and progression." (PMID 31587474, 2019). "The single loss of PAK2 sufficed to interfere with tumour development." (PMID 28707321, 2017). "In addition, overexpression of the PAK2 and pSer20PAK2 proteins in patients was significantly linked to negative clinicopathologic factors, such as advanced tumor stage, positive distant metastasis, increased lymph node metastasis, and deeper tumor depth." (PMID 39769207, 2024). "Elevated PAK2 expression correlated with advanced tumor progression, poor prognosis, and clinical staging in malignancies." (PMID 40612101, 2025). "Functional studies revealed that PAK2 overexpression positively correlates with malignant phenotypes such as metabolic reprograming and tumor metastasis." (PMID 41311809, 2025). "The pharmacological inhibition of Pak1/Pak2 and silencing Pak1/Pak2 using siRNA reduced the tumor cell metabolism—reduced ECAR and OCR." (PMID 40090587, 2025). "Through a literature review, we ascertained that PAK2 promote the proliferation, migration, and invasion of tumor cells, which was conjectured to be related to the impact of PAK2 on the infiltration of CD4+ T cell immunity." (PMID 40332759, 2025). "Collectively, our findings elucidated a novel tumor-suppressive role of PPP1R12B in HCC through modulation of the PAK2/β-catenin/Cyclin D1 axis." (PMID 40612101, 2025). "p21-activated kinase 2 (PAK2) plays a critical role in cytoskeletal remodeling and is frequently associated with advanced tumor progression and poor prognosis." (PMID 41423632, 2025). "Across four HCC datasets (GSE22058, GSE36376, GSE14520, OEP000321), both PAK2 and β-catenin showed significantly higher expression in tumor tissues versus adjacent non-tumor tissues." (PMID 40612101, 2025). "Through GO and KEGG enrichment analysis of the coDEGs of single CTCs and CTC clusters, PAK2 was shown to increase cell-cell adhesion to promote tumor cell aggregation." (PMID 41423632, 2025).
tumor (continued). "Spatial transcriptomics and single-cell sequencing analyses revealed PAK2's specific expression patterns within the tumor microenvironment, confirming its influence on the activity of immune-related molecules and immunomodulators." (PMID 41311809, 2025). "Mechanistically, PAK2 promoted tumor cell proliferation, migration, and invasion by regulating actin dynamics through the LIMK1/cofilin signaling pathway." (PMID 38828848, 2024). "Cell communication analysis revealed that overexpression of PAK2 promotes communication between cancer cells and the tumor microenvironment." (PMID 38343537, 2024). "PAK2 overexpression has been extensively studied across different cancer types, revealing its multifaceted roles in tumor progression, metastasis, and resistance to therapies." (PMID 39769207, 2024). "Accordingly, miR-195 was a target of hsa_circ_0013401, while PAK2 was a target of miR-195 (tested through reporter assays) and in a mouse xenograft model, hsa_circ_0013401 enhanced tumour formation and progression through the regulatory axis of miR-195/PAK2." (PMID 36983973, 2023). "In the survival analysis of pan-cancer patients, high expression of PAK1, PAK2, PAK4, and PAK6 as well as the low expression of PAK7 was mainly associated with poor prognosis of tumor patients." (PMID 36064705, 2022). "PAK2 has been shown to modulate differentiation, motility, and attachment in a large number of cellular contexts, including tumor cells." (PMID 35333693, 2022). "To verify the effect of RP11-499E18.1 and PAK2 overexpression on tumor development, we implanted pcDNA-RP11-499E18.1 or pcDNA-RP11-499E18.1 plus pcDNA-PAK2 transfected CaOV3 cells into the nude mice." (PMID 34621737, 2021). "IHC results also showed that circ_0013401 overexpression notably increased the levels of PAK2 and Ki67 expression, and circ_0013401 knockdown dramatically lowered the levels of PAK2 and Ki67 expression in NB tumor tissues." (PMID 34853631, 2021). "Many studies have found that PAK2 is abnormally expressed in many tumors and can even be used as a tumor treatment target." (PMID 33878735, 2021). "More importantly, these tumor-promoting effects triggered by PAK2 overexpression were distinctly reversed by SOX2 knockdown." (PMID 34621737, 2021). "Based on results of our in vitro experiments, we sought to further verify the regulatory effects of circ_0013401 on NB tumor growth and miR-195/PAK2 expression in vivo." (PMID 34853631, 2021). "Transcriptomics analysis of various CD4+ T cell subsets from patient tumours, normal surrounding tissue and peripheral blood revealed that tumour-localising Tregs have unique signatures of upregulated genes including pak2." (PMID 33573141, 2021). "Studies have found that PAK2 plays important roles in tumor cell proliferation, invasion, apoptosis and so on." (PMID 33878735, 2021). "Using TCGA data, Zhu and colleagues demonstrated that PAK2 was up-regulated in tumour tissue in comparison with normal samples and this result has been confirmed by protein expression in paired tumour/normal tissue samples." (PMID 32429269, 2020). "We also examined the expression levels of JUP (gene for plakoglobin), CD44, and PAK2 in CTCcl+ vs. CTCcl− TNBC PDX models as they were reported to have a role in tumor cell aggregation/CTCcl formation and subsequent metastasis." (PMID 31652963, 2019). "In a recent study, intercellular CD44 homophilic interactions and its subsequent interactions with PAK2 were reported to mediate tumor cell aggregation and polyclonal metastasis in BC PDX models." (PMID 31652963, 2019). "To validate the results of in silico studies, we performed PAK2 immunoblotting in 26 HNC tumor samples, wherein 24 tumor samples showed PAK2 overexpression in comparison to normal counterpart." (PMID 30068946, 2018).